TLX2 (T cell leukemia homeobox 2)
Description:
Transcription activator that binds DNA elements with the consensus sequence 5'-CGGTAATTGG-3'. Binds DNA via its homeobox. Required for normal cell death of enteric neurons in the gastrointestinal tract. Required for normal development of the enteric nervous system, and for proper development of normal motility of the gastrointestinal tract (By similarity).
Synonyms: HOX11L1; NCX; Enx
Tractability: PROTAC: ubiquitination databases record sites on it.
Gene: Protein-coding gene on chromosome 2 (74,513,463 to 74,517,148, forward strand). Ensembl gene ENSG00000115297.
Subcellular location: Nucleus
Subcellular location (Human Protein Atlas): Nucleoplasm
Gene Ontology:
Molecular function: DNA-binding transcription activator activity, RNA polymerase II-specific; protein binding; sequence-specific DNA binding; sequence-specific double-stranded DNA binding; DNA-binding transcription factor activity, RNA polymerase II-specific; DNA binding; DNA-binding transcription factor activity
Biological process: positive regulation of transcription by RNA polymerase II; animal organ development; regulation of transcription by RNA polymerase II; regulation of DNA-templated transcription
Cellular component: chromatin; nucleus; cytoplasm
Genetic constraint (gnomAD): Loss-of-function variants: 15 observed, 18.07 expected, observed/expected ratio (o/e) 0.83, 90% interval 0.55 to 1.28. The synonymous counts are far from expectation, so gnomAD's model fits this gene poorly and the ratio says little. Missense variants: 384 observed, 381.29 expected, observed/expected ratio (o/e) 1.01, 90% interval 0.93 to 1.1. Synonymous variants: 213 observed, 171.89 expected, observed/expected ratio (o/e) 1.24, 90% interval 1.11 to 1.39.
Homologues: Orthologues: chimpanzee TLX2 (99% identical), macaque TLX2 (99% identical), guinea pig TLX2 (95% identical), dog TLX2 (94% identical), pig TLX2 (94% identical), mouse Tlx2 (93% identical), rabbit TLX2 (93% identical), rat Tlx2 (92% identical). Paralogues in human: TLX1 (61% identical), TLX3 (59% identical), HOXB3 (23% identical), HOXD3 (22% identical), HOXB2 (21% identical), HOXA3 (21% identical), HOXA2 (21% identical), HOXD1 (20% identical), PDX1 (20% identical), HOXA10 (18% identical), HOXB4 (18% identical), HOXC4 (18% identical), and 30 more.
Diseases named in the same sentence as TLX2 in open-access papers:
TLX2 is named in the same sentence as 33 diseases in open-access papers, as found by Europe PMC text mining. Sharing a sentence is not in itself a finding about the gene and the disease. The quoted sentences say what the papers report.
Intestinal neuronal dysplasia (2 papers, 2017 to 2020). "Tlx2 deficiency leads to megacolon and myenteric neuronal hyperplasia in mice, which may explain its association with intestinal motility disorders like Intestinal neuronal dysplasia (IND)." (PMID 28403821, 2017).
uterine sarcoma (2 papers, 2020 to 2022). "T-cell leukemia homeobox 2 (TLX2) has prognostic value in uterine sarcoma." (PMID 35676660, 2022).
alcoholism (1 paper, 2023). "In this study, we found that TLX2 was associated with ribosomes, amphetamine addiction, cocaine addiction, alcoholism, and dopaminergic synapses in pan cancer." (PMID 37758722, 2023). "Five pathways, including ribosomes, amphetamine addiction, cocaine addiction, alcoholism, and dopaminergic synapses, may be the main pathways through which TLX2 mediates tumorigenesis and progression." (PMID 37758722, 2023).
embryonal carcinoma (1 paper, 2021). A non-seminomatous malignant germ cell tumor characterized by the presence of large germ cells with abundant cytoplasm resembling epithelial cells, geographic necrosis, high mitotic activity, and pseudoglandular and pseudopapillary structures formation. "TLX2 is also regulated by the BMP-pathway as shown in murine mesoderm development and embryonal carcinoma cells." (PMID 33539429, 2021).
endometrial cancer (1 paper, 2023). Primary or metastatic malignant neoplasm involving the endometrium (mucous membrane that lines the endometrial cavity). "Among candidate genes, ARX, POU2F3, TLX2 and LIM1 were derived as molecules contributing to the malignant transformation of endometrial cancer." (PMID 36969081, 2023).
gastrointestinal stromal tumor (1 paper, 2017). "The TF obtained commonly for COAD, PHOX2B, is related to TLX2, a gene which has been shown to play a role in the tumorigenesis of gastrointestinal stromal tumors." (PMID 28347313, 2017).
Hodgkins lymphoma (1 paper, 2022). A heterogeneous group of malignant lymphoid neoplasms of B-cell origin characterized histologically by the presence of Hodgkin and Reed-Sternberg (HRS) cells in the vast majority of cases. "PBX1 was upregulated in Hodgkin lymphoma and affected the differentiation of Hodgkin lymphoma cells by activating NFIB and TLX2." (PMID 35068042, 2022).
omphalocele (1 paper, 2025). Omphalocele is an embryopathy classified in the group of abdominal celosomias and is characterized by a large hernia of the abdominal wall, centered on the umbilical cord, in which the protruding viscera are protected by a sac. "Interestingly, Hand1 conditional deletion employing Tlx2-cre also reveals an omphalocele phenotype." (PMID 40960281, 2025).
ovarian carcinoma (1 paper, 2023). A malignant neoplasm originating from the surface ovarian epithelium. "TLX2 expression was significantly upregulated in ovarian cancer cell lines compared to ovarian epithelial cell lines." (PMID 37758722, 2023).
pan (1 paper, 2023). "In this study, we investigated whether TLX2 in pan cancer was associated with immune infiltration and immune checkpoint genes." (PMID 37758722, 2023). "This study reveals the potential mechanism of TLX2 in pan cancer based on data obtained from various datasets." (PMID 37758722, 2023). "In this study, we investigated the correlation between TLX2 expression and prognosis of pan cancer." (PMID 37758722, 2023). "Therefore, in this study, we explored the possible role of TLX2 in pan cancer." (PMID 37758722, 2023). "In pan cancer, NXF2B, MSLNL, PCGF1, INO80B-WBP1, LBX2-AS1, MRPL53, LBX2, TTC31, WDR54 and WBP1 were co-altered in the TLX2-altered group." (PMID 37758722, 2023).
retinoblastoma (1 paper, 2024). A malignant tumor that originates in the nuclear layer of the retina. "Three genes from the ‘cancer’ and ‘neuro’ group are overlapping (ALK, TLX2, THY1), with THY1 being also directly connected to retinoblastoma." (PMID 39695086, 2024).
type 2 diabetes mellitus (1 paper, 2019). A type of diabetes mellitus that is characterized by insulin resistance or desensitization and increased blood glucose levels. "Based on our findings, the highly activated motifs of transcription factors FOXD1/2, PATZ1, and TLX2, were associated with the reported adverse effect, “Type II diabetes mellitus (Type II DM)”, a novel observation in this study." (PMID 31772269, 2019).
tumor (4 papers, 2015 to 2023). "High expression of TLX2 in four tumors was significantly associated with tumor stage." (PMID 37758722, 2023). "Our data indicated tumor suppressor activity of RYBP in HL which thereby contributed to elevated TLX2 expression." (PMID 33539429, 2021). "Our work elucidated the potential role of TLX2 in tumor immunity." (PMID 37758722, 2023).
cancer (3 papers, 2019 to 2024). A tumor composed of atypical neoplastic, often pleomorphic cells that invade other tissues. "Expression of TLX2 was significantly associated with MSI in seven cancer types and TMB in five cancer types." (PMID 37758722, 2023). "TLX2 can be a candidate diagnostic and prognostic factor in a variety of cancers." (PMID 37758722, 2023). "Abnormal TLX2 expression in pan cancer may be associated with the development and progression of these tumors." (PMID 37758722, 2023). "Second, we explored the possible regulatory network and drug sensitivity of TLX2 in pan cancer, and the specific mechanisms of TLX2 in pan cancer development and progression need to be further investigated." (PMID 37758722, 2023). "Bioinformatics and experimental validation represent a useful way to explore the mechanisms and functions of TLX2 gene in the cancer disease process from a pan cancer perspective." (PMID 37758722, 2023). "This study explored the role of TLX2 in pan cancer and laid the foundation for the use of TLX2 as a new diagnostic and prognostic molecular marker and therapeutic strategy." (PMID 37758722, 2023). "First, this study explored the clinical significance and genomic variation of TLX2 aberrant expression in pan cancer based on public databases, and these may require real-world samples for validation in the future." (PMID 37758722, 2023). "Aberrant expression of TLX2 in pan cancer may promote tumorigenesis and progression through different mechanisms." (PMID 37758722, 2023). "TLX2 was aberrantly expressed in pan cancer and cell lines and correlated with clinical stage." (PMID 37758722, 2023). "In the present study, we found that TLX2 was aberrantly expressed in pan cancer." (PMID 37758722, 2023). "Expression of TLX2 may affect the response of cancer patients to immune checkpoint therapy, which will help us to further explore the mechanisms of TLX2-based immunotherapy in pan cancer." (PMID 37758722, 2023). "Thus, it was decided to use the cBioPortal database to discover that amplification is the greatest frequency of TLX2 alterations in pan cancer." (PMID 37758722, 2023). "These suggested that TLX2 may be a promising prognostic marker in pan cancer." (PMID 37758722, 2023). "TLX2 may represent an important therapeutic target for human cancers." (PMID 37758722, 2023). "However, there are no relevant studies on TLX2 gene alterations in human cancers." (PMID 37758722, 2023).
TLX2 also shares sentences with these, for which no sentence is quoted: heart failure (5 papers); colon cancer (2); megacolon (2); neuroblastoma (2); systemic lupus erythematosus (2); Arrhythmia (1); cardiac diseases (1); cardiac hypertrophy (1); cardiac ischemia (1); cocaine addiction (1); hypertensive heart disease (1); infection (1); intestinal motility disorders (1); lupus nephritis (1); lymph node metastasis (1); medulloblastoma (1); rheumatic diseases (1); Sepsis (1); ventricular tachycardia (1).